BRAF (B-Raf proto-oncogene, serine/threonine kinase)
Diseases named in the same sentence as BRAF in open-access papers (continued):
Sharing a sentence is not in itself a finding about the gene and the disease.
melanoma (continued). "However, we found three cases of BRAF T599I variants, and it has been suggested that vemurafenib might control cancer, such as melanoma, even in patients with that variant." (PMID 37007070, 2023). "To test the hypothesis that distinct cellular subpopulations and transcriptional programs underlie clinical differences between BRAF wildtype and V600E variant brain metastases, we performed snRNA-seq on treatment-naive BRAF wildtype (n = 3) and BRAF V600E variant (n = 3) melanoma brain metastases." (PMID 37589977, 2023). "Thus, the combination with S63845 may be considered for already established BRAF inhibitors in BRAF-mutated melanoma, and the combination of SCH772984 with S63845 could be a new therapeutic option for all melanomas." (PMID 36902392, 2023). "Furthermore, BRAF V600E mutation in EV-associated nucleic acids isolated from exudative seroma of stage III melanoma patients could serve as a minimal residual disease/prognostic indicator to identify patients at risk of relapse." (PMID 37627054, 2023). "However, its role in BRAF as compared to NRAS mutated melanoma needs further investigation." (PMID 36982192, 2023). "After these trials demonstrated that the combination of BRAFi/MEKi/ICI could be an active treatment option for BRAF-mutated melanoma, further studies were carried out to identify candidate patients who may better benefit from this approach and the correct use of the new tools." (PMID 36995534, 2023). "Thus, in three BRAF-mutated melanoma cell lines, we investigated whether iron unbalance and lipid peroxidation may be a part of the molecular mechanisms underlying the antimelanoma activity of HPF." (PMID 37507910, 2023). "Melanoma has the highest propensity to form brain metastases of all malignancies and given that melanoma patients have a high incidence (10-40%) of developing metastases in the brain, the clinical relevance of BRAF mutational status in melanoma brain metastasis has been studied." (PMID 37920169, 2023). "However, considering that this metabolic adaptation has been observed in both melanoma cells with different BRAF mutation and in etoposide resistant neuroblastoma cells, we believe that this response is neither cancer-type specific nor related to the specific drug-induced cytotoxic effect." (PMID 37534247, 2023). "This agrees with current clinical practice which uses mTOR and BRAF inhibitors as first-line therapy for kidney cancer and melanoma, respectively, since the c-Met/mTOR axis is frequently altered in kidney cancer while BRAF mutations are the main genetic drivers of melanoma." (PMID 38041118, 2023). "Therefore, synthetic glucocorticoids may be coadministered with lj‐2‐66 to boost the potential therapeutic efficacy of the latter for melanoma harboring BRAF mutations." (PMID 35332658, 2022). "Notably, KSR2 has also been linked to MAPK pathway reactivation and resistance to BRAF+MEK inhibition in melanoma cells, thus suggesting that the roles of KSR1 or KSR2 in modulating the response to KRAS/MAPK pathway inhibition may have been underestimated." (PMID 35313064, 2022). "Notably, while these studies were conducted with SK-MEL-28 cells, which express mutant BRAF (the V600E mutation), results obtained with other melanoma BRAF mutant or wild type cells may differ." (PMID 35265066, 2022). "Moreover, BRAF mutations participate in the metastatic spread of melanoma." (PMID 35974375, 2022). "However, BRAF-mutated melanomas treated with these compounds almost invariably develop resistance." (PMID 36686679, 2022). "It is currently unknown whether BRAF/MEK targeted therapy or immunotherapy alone or the combination of targeted therapy with immunotherapy should be considered the first line of therapy in BRAF-mutated melanoma." (PMID 35308763, 2022).
melanoma (continued). "Several previous studies have demonstrated that BRAF deletion mutations can occur in melanoma, pancreatic cancer, and thyroid cancer; in addition, activating BRAF deletion mutations might serve as a type of resistance mechanism to BRAF inhibitors plus MEK inhibitors." (PMID 35433454, 2022). "Although immunotherapy is associated with lower overall response rates (ORR) in patients with BRAF-mutated melanoma, using checkpoint inhibitors in combination with BRAF inhibitors and MEK inhibitors may provide a more durable response that is less susceptible to spontaneous resistance." (PMID 35954441, 2022). "Data for unique BRAF mutants may be obtained from case reports or case series of patients with advanced melanomas, as well as other tumor entities for which BRAF mutations have been described, such as thyroid, colorectal, or non-small cell lung cancer (NSCLC) [14••]." (PMID 35380338, 2022). "Therefore, we speculated that glycolysis may be a potential target for the treatment of melanoma and studied in human melanoma cells with BRAF mutation." (PMID 36188586, 2022). "Cox analysis was performed in BRAF WT and BRAF mutated primary melanomas to elucidate if miR-125b, miR-200c and miR-205 had, on their own, a relevant influence on distant metastasis-free survival and melanoma-specific survival as independent prognostic factors of clinical outcomes (DMFS and MSS)." (PMID 35326682, 2022). "A potential future area of investigation could also examine the effectiveness of second-line ipilimumab in BRAF-mutated melanoma patients after progression on first-line nivolumab or pembrolizumab and the comparative effectiveness between ipilimumab monotherapy and BRAFi/MEKi combination." (PMID 35456332, 2022). "In addition, 4% of melanomas resistant to BRAF inhibitors showed mutations in Akt, Phosphatase and Tensin Homolog (PTEN), and Phosphoinositol-3-Kinase (PI3K), along with other regulatory genes of the PI3K–Akt pathway associated with the development of drug resistance." (PMID 35335966, 2022). "In addition, immunotherapeutic drugs combined with other classical drugs have also shown good efficacy in a variety of tumors, such as ICIs combined with angiogenesis inhibitors for liver cancer or combined with BRAF inhibitors for advanced melanoma with BRAF V600 mutation." (PMID 35918500, 2022). "Furthermore, miR-125b may be used as a specific biomarker for BRAF mutated primary melanomas to predict distant metastasis-free survival and melanoma-specific survival, which suggests that it could be involved in melanoma progression." (PMID 35326682, 2022). "Since half of the total melanomas show the V-raf murine sarcoma viral oncogene homolog B1 (BRAF) mutation, they may respond to targeted therapies with BRAF (vemurafenib, dabrafenib, encorafenib) and/or mitogen-activated protein kinase (MEK) inhibitors (trametinib, cobimetinib, binimetinib)." (PMID 36500861, 2022). "High expression of genes in the IFN-γ signature was also found to be a prognostic factor in BRAF mutated melanoma patients with resected stage III A–C (AJCC 7th edition) disease regardless of whether they received dabrafenib and trametinib or placebo in the adjuvant setting." (PMID 35892846, 2022). "Assuming that the duration of BRAF-inhibition is short, the potential association with immune-checkpoint therapies that modulate the immune system could improve the in vivo management of patients with advanced melanoma." (PMID 35565234, 2022). "Therefore, miR-125b, miR-200c and miR-205 could be used as prognostic biomarkers for metastasis development and melanoma survival in a BRAF mutational status-independent manner." (PMID 35326682, 2022). "In addition, studies have been undertaken to carry out genomic analyses to predict survival or treatment response in mutated BRAF melanoma, but these studies all used tumour tissue and, in most cases, few samples were taken, due to the risks involved in rebiopsy, among other considerations." (PMID 35203494, 2022).
melanoma (continued). "Recent findings published on anti LAG-3 agent relatlimab have opened a completely new perspective on metastatic melanoma treatment with really encouraging data in terms of PFS that, if confirmed in OS, may lead to a new standard of treatment both for WT and BRAF mutated melanoma." (PMID 35160279, 2022). "An explanation could be that BRAF-mutated melanoma cells express high levels of COX-2." (PMID 35956175, 2022). "Therefore, it is an urgent task to develop new drugs for melanomas with BRAF mutations." (PMID 35332658, 2022). "In the COMBI-AD trial, adjuvant therapy with the BRAF inhibitor dabrafenib in combination with the MEK inhibitor trametinib resulted in a significantly lower risk of recurrence in patients with stage III melanoma with BRAF V600E or V600K mutations compared with placebo." (PMID 35538491, 2022). "Besides, in approximately 40–50% of melanomas, tumors are driven by oncogenic BRAF mutations." (PMID 36428582, 2022). "Hence, combining Vem with such agents may provide new insights to overcome the resistance of Vem to BRAF mutated melanoma." (PMID 36034784, 2022). "Trametinib is a selective MEK1/2 kinase inhibitor indicated, in combination with the BRAF inhibitor dabrafenib, for the treatment of patients with unresectable or metastatic melanoma with BRAF V600E or V600K mutations or in the adjuvant setting of V600E- or V600K-positive melanomas." (PMID 35380338, 2022). "Interestingly, the integral role of BIM in promoting apoptosis in response to molecular targeted therapies has been determined in BRAF-mutant colorectal cancer cells, BRAF-mutated melanoma cells, BCR–ABL-positive leukemia cells, and EML4-ALK-positive NSCLC cells." (PMID 36553449, 2022). "Furthermore, about 10% of melanoma patients may show an intertumorally discordant BRAF status, and about 15% of BRAF-mutated melanomas may show intratumor BRAF heterogeneity." (PMID 36551302, 2022). "Data obtained in SK-MEL-28 cell line are consistent with the one obtained in primary BRAF mutated melanoma cells, thus highlighting that the use of a Nox4 inhibitor could potentiate the current therapeutic strategy to treat melanoma patients with BRAF mutations." (PMID 33451139, 2021). "Additionally, VERU-111 showed a giant potential to overcome Vem-resistance in melanoma cancer cells, which may be advantageous for melanoma patients harboring BRAF(V600E) mutation." (PMID 33841154, 2021). "Acquired resistance to BRAF/MEK inhibitors seems to cause increased production of reactive oxygen species (ROS) in BRAF V600E mutant melanoma cells; this production could be exacerbated and exploited by therapeutic inhibition of HDAC and subsequent downregulation of the SLC7A11 transporter." (PMID 34440824, 2021). "Moreover, BRAF-targeted therapy may add another strategy for improving clinical outcomes in patients with BRAF-mutated melanoma." (PMID 34829495, 2021). "While melanoma is recognized to exhibit high heterogeneity, a BRAF V600E mutation present in a gene encoding a member of the Ras/MAPK (mitogen-activated protein kinase) signaling pathway is a predominant genetic aberration detected in over 40% of melanoma patients." (PMID 33918883, 2021). "Indeed, single cells genotyping showed that BRAF activating mutations may coexist in different cells of the same melanoma." (PMID 34208446, 2021). "Importantly, high levels of MMP9 and BRAF V600E MTs are associated with poor progression-free survival in melanoma patients, and activation of NRF2 through this pathway might be critical for tumor cell proliferation." (PMID 34069882, 2021). "Moreover, even in the primitive melanoma, the neoplastic component could be scant, making the identification of BRAF mutation unsuccessful." (PMID 34207125, 2021).
melanoma (continued). "Although the concordance rate of the BRAF mutation status between primary melanoma and metastases is quite high, a recent meta-analysis showed a pooled discrepancy rate of 13.4% between primary melanomas and metastases and a 7.3% discrepancy rate between metastatic sites." (PMID 33915880, 2021). "Interestingly, while each of these melanoma models harbored a BRAF mutation, single-agent treatment with an experimental direct OXPHOS inhibitor, IACS-010759, significantly improved the survival of mice- and had greater effects on brain metastases than on lung metastases or primary tumors." (PMID 34859235, 2021). "Moreover, clinical studies have reported that patients with melanoma carrying BRAF mutation and PTEN inactivation showed a trend for shorter median progression-free survival (PFS) on BRAF inhibitor-targeted therapy than patients with melanoma having wild-type PTEN19,20." (PMID 34282258, 2021). "Our results support the notion that further activation of MAPK signaling through loss of inhibitors such as DUSP4 in melanoma cells that already harbor activating BRAF or NRAS mutations is detrimental, a hypothesis that will need to be explored with further experiments." (PMID 32767816, 2021). "Overall, these studies show that the constitutive ERK activation, as found in BRAF-mutated melanomas, may favor an ineffective anti-tumor immune response, indicating that a targeted inhibition of MAPK signaling may reverse these immunosuppressive effects as outline below." (PMID 34576054, 2021). "In a BRAF‐mutated melanoma, this T‐cell response could be amplified, by broadening the TCR repertoire at baseline (BRAF/MEK inhibitors) and by subsequently increasing the number of proliferating CD4+ T cells (checkpoint inhibitors), thus improving the likelihood of a positive ICI therapy response." (PMID 33449393, 2021). "The MAPK pathway represents the most dysregulated site in melanoma and is fundamental for the uncontrolled cell proliferation and differentiation; about 50–60% of all melanomas are characterized by a somatic mutation of serine/threonine protein kinase BRAF, in the codon V600E." (PMID 33917181, 2021). "However, the effect of vemurafenib in the treatment of metastatic BRAF mutated colorectal cancer is less potent than in BRAFV600E melanoma, and its clinical efficacy as monotherapy in BRAF mutant metastatic colorectal cancer is reduced due to the high incidence of fast-developing chemoresistance." (PMID 34639107, 2021). "Furthermore, BRAF-mutated melanomas may create a TME that inhibits T cell effector functions even more effectively." (PMID 34576054, 2021). "Thus, the apparent opposite observations seen in CRC and melanoma means that, in addition to BRAF mutations, other intrinsic parameters might be involved in the shaping of the tumor microenvironment (TME) including the development of TLS." (PMID 34276690, 2021). "Interestingly, it has been demonstrated that PLX4720—a BRAF inhibitor used to treat BRAF-mutated melanoma cells—leads to the activation of melanoma associated fibroblasts causing ECM remodelling, which triggers increased integrin β1/FAK/Scr signalling in melanoma cells." (PMID 33803675, 2021). "Thus, the combination therapy mixtures consisting of RAF and MEK specific blockers (e.g., trametinib (U.S. Food and Drug Administration (FDA)-approved MEKi) and dabrafenib (FDA-approved BRAFi)) have emerged as the standard therapy for melanoma patients harboring hotspot BRAF-V600E mutations." (PMID 33808483, 2021). "Also, the combination of vemurafenib and cobimetinib had a better outcome than vemurafenib alone in a phase 3 randomized clinical trial performed on 495 patients with previously untreated, unresectable, locally advanced, or metastatic BRAF V600 mutation-positive melanoma (coBRIM)." (PMID 34447613, 2021).
melanoma (continued). "Indeed, it has been shown that in patients with advanced BRAF mutated melanoma undergoing treatment with TT, higher levels of plasma circulating tumour DNA (ctDNA) may predict disease progression earlier than imaging and/or clinical assessments." (PMID 33801689, 2021). "Treatment of these cells with different doses of the chemotherapy drugs (BRAF inhibitor), dabrafenib or vemurafenib, used in melanoma treatment revealed that USP7- or EZH2-deficient cells were more sensitive to chemotherapeutics, which could be partially rescued by FOXO1 knockdown." (PMID 33849069, 2021). "Thus, plasma cfDNA-based tests could allow for easy rechecking of the BRAF mutation status in patients with advanced melanoma and correct diagnoses." (PMID 34298804, 2021). "Interestingly, BRAF (V600E) mutation in nevi involves initial cell proliferation and is followed by oncogene-induced ageing, most likely as a part of the accumulation of p16 INK4a; in melanoma BRAF (V600E), mutations only induce uncontrolled proliferation." (PMID 34203771, 2021). "Notably, PLA1A can be used as a diagnostic marker for an efficient discrimination between naïve melanoma samples and advanced melanoma samples (sensitivity 91%, specificity 57%, and AUC 0.99), as well as BRAF-mutated melanoma samples (sensitivity 62%, specificity 61%, and AUC 0.75)." (PMID 33723350, 2021). "Indeed, sensitivity to BRAF and MEK inhibitors, a feature of BRAF addiction, has been associated with distinct phenotype plasticity of the differentiation state and global alterations in gene expression programs in BRAF-mutated melanomas." (PMID 33793658, 2021). "However, others have reported that galectin-3 may act as a metastasis suppressor or even sensitize BRAF-mutated melanoma cells to vemurafenib (BRAF V600E inhibitor) treatment." (PMID 33918883, 2021). "However, BRAF mutations are not limited to melanoma patients." (PMID 33799327, 2021). "Thus, combining T-VEC and BRAF/MEK inhibition might represent a potentially promising avenue to enhance T-VEC efficacy in BRAF-mutated and BRAF-wildtype melanoma and requires further pre-clinical and clinical validation." (PMID 33925915, 2021). "A two-fold increase in melanin production, after 2 mM Caff treatment, was found in both Mel1 and Mel3 cells, thus confirming the in silico data and supporting the hypothesis that Caff inhibits the growth of BRAF-mutated melanoma cells through a differentiation-inducing pathway." (PMID 34199192, 2021). "Additionally, G9a targeted therapies may help a wider range of melanomas, since the amplification of G9a occurs in the context of both BRAF- and NRAS-activating mutations, which are the two most common oncogenic drivers of melanoma." (PMID 34691767, 2021). "However, we show that UVR-driven mucosal melanomas harbor high frequency BRAF mutations, so could benefit from BRAF and MEK targeted therapies." (PMID 33431815, 2021). "However, this impairment of WNT5A signaling appears to trigger a compensatory mechanism to maintain the invasive migration of BRAF wild‐type and BRAFV600 mutated melanoma cells treated with a BRAF inhibitor, through a RND3‐RhoA‐induced transition from a mesenchymal to an amoeboid mode of invasion." (PMID 33969605, 2021). "For example, although mutational activation of BRAF is an early event in melanomagenesis, mutations in cooperating oncogenes or tumor suppressors such as PTEN, RAC1, or CDKN2A that often co-occur with BRAF mutation may influence the regulation of autophagic flux in malignant melanoma cells." (PMID 34298710, 2021). "Moreover, Ocoxin reduced the tumor area of BRAF-mutated melanoma metastasis in the lung in vivo." (PMID 33669949, 2021). "Predictive biomarkers may help including patients within a specific category, such as for the mutational status of a given gene (BRAF in melanoma, cERB-B2 in breast or EGFR in non-small-cell lung cancers), or indicate a continuous variable, such as the PDL-1 staining percentage." (PMID 35008245, 2021).